TREM2 (triggering receptor expressed on myeloid cells 2)
Diseases named in the same sentence as TREM2 in open-access papers (continued):
Sharing a sentence is not in itself a finding about the gene and the disease.
Alzheimer disease (continued). "A decade of GWAS projects for Alzheimer’s disease has provided key and initially surprising insights into the progression of late-onset Alzheimer’s disease, particularly the dependence on the innate immune system, with the identification of genes such as TREM2 and SPI1/PU.1." (PMID 32274467, 2019). "Also, rare variants in TREM2 and APP genes were associated with Alzheimer’s disease." (PMID 28449691, 2017). "TREM2 forms a receptor signaling complex with TYROBP, which triggers the activation of immune responses in macrophages and dendritic cells, and the functional polymorphism of TREM2 is reported to be associated with neurodegenerative disorders such as Alzheimer’s disease (AD)." (PMID 26332043, 2015). "Thus, this study provides important insights into TREM2-related signaling, which could be used as a platform for further experiments into the pathophysiological basis of late-onset Alzheimer's disease." (PMID 23855984, 2013). "In replication analyses, 21 genes showed nominal support in UK Biobank and Alzheimer's Disease Genetics Consortium (ADGC) cohorts, with eight genes (TREM2, ACADS, MFSD12, NUP210L, PIEZO2, PSEN1, SMURF2, AKAP13) supported under identical masks." (PMID 41960309, 2026). "It is encouraging to note that human safety of the TREM2 agonist AL002C has been established 48, and it is advancing through Phase III of clinical evaluation for Alzheimer's disease." (PMID 41041054, 2025). "In Alzheimer’s disease cohorts with whole genome sequencing and tau and amyloid-β, the authors show that sex, APOE-ε4 and TREM2 impact tau via both Aβ and tau pathways." (PMID 40595476, 2025). "DAM, first described in Alzheimer’s disease models, are characterized by downregulation of homeostatic markers like P2RY12 and CX3CR1, and upregulation of Trem2, Apoe, Axl, and Spp1." (PMID 40934003, 2025). "Next, because only APOE genotyping was available in MAS, rare genetic variants associated with Alzheimer’s disease (e.g., TREM2, PSEN1, and other SNPs) were not assessed, and therefore associations between subjective concern trajectories and these genetic mechanisms could not be examined." (PMID 41374454, 2025). "The microglial surface protein Triggering Receptor Expressed on Myeloid Cells 2 (TREM2) plays a critical role in mediating brain homeostasis and inflammatory responses in Alzheimer’s disease (AD)." (PMID 40928206, 2025). "Triggering receptor expressed on myeloid cells 2 (TREM2), a receptor on microglial membranes, has emerged as a research focus in Alzheimer’s disease (AD), supported by the positive results of genome-wide association studies (GWAS) over the past decade." (PMID 38841103, 2024). "Triggering receptor expressed on myeloid cells 2 (TREM2) plays a critical role in microglial activation, survival, and apoptosis, as well as in Alzheimer’s disease (AD) pathogenesis." (PMID 38172904, 2024). "For example, in Alzheimer’s disease, DAM have been characterized by the upregulation of genes such as apolipoprotein E (APOE) and triggering receptor expressed on myeloid cells 2 (TREM2) while downregulating genes involved in synaptic function and homeostasis." (PMID 37511539, 2023). "By utilizing existing clinical date from DisGeNET and undergoing protein-protein network analysis on cholesterol metabolism and Alzheimer’s disease, the top target genes selected were GSK3B, BACE1, SREBP2, CYP46A1, ABCA1, and TREM2." (PMID 37444065, 2023). "Together with its receptor, triggering receptor expressed on myeloid cells 2 (TREM2), TYROBP contributes to the onset and progression of Alzheimer's disease by impacting various cellular processes such as phagocytosis, cytokine production, and inflammation." (PMID 38017559, 2023). "The advancing body of research on TREM2 has markedly deepened our comprehension of glioblastoma (GBM) and Alzheimer’s disease (AD), with a particular emphasis on the activation and inflammatory response of microglia/macrophages." (PMID 38203185, 2023).
Alzheimer disease (continued). "This is consistent with our previous findings in the Dominantly Inherited Alzheimer’s Disease Network (DIAN) cohort, where soluble TREM2 increases as early as 21 years before symptom onset." (PMID 37775827, 2023). "Further analysis of the mRNA level of other phagocytosis-related genes which were involved in the pathomechanism of Alzheimer’s disease demonstrated that JQ1 significantly reduced the expression of Cd33, Trem2, and Zyx." (PMID 36613460, 2022). "The robust inflammation observed in ApoE4-expressing microglia is driven by increased expression of TREM2 and the TREM2-APOE signaling pathway, a major regulator of microglial functions in Alzheimer’s disease." (PMID 36077289, 2022). "In this context, we highlight microglial TREM2 and CSF1R as emerging targets for disease-modifying therapy in Alzheimer’s disease (AD) and other neurodegenerative disorders." (PMID 33652870, 2021). "Another report of Alzheimer’s disease is that the significantly decreased plaque load observed in APP transgenic and APOE or TREM2 knockout mice." (PMID 34867158, 2021). "Increased soluble TREM2 (sTREM2) levels in CSF have been found in HIV infection, multiple sclerosis (MS), and Alzheimer's disease (AD)." (PMID 32117023, 2020). "We investigated the levels in cerebrospinal fluid (CSF) of glial proteins YKL-40, soluble TREM2 (sTREM2) and progranulin in DLB and their relationship with Alzheimer’s disease (AD) biomarkers." (PMID 31127154, 2019). "TREM2 is a transmembrane protein that interacts directly with TYROB, a downstream adapter molecule, which are both also upregulated in a mouse model of Alzheimer’s disease." (PMID 30705335, 2019). "In Alzheimer’s disease, activated microglia expressing galectin-3 bind to TLR4 (Toll-like receptor 4), MerTK, and TREM2 (triggering receptor expressed on myeloid cells 2), which facilitates amyloid-beta clearance and promotes inflammatory responses associated with the disease." (PMID 40429840, 2025). "Interestingly, several upregulated DE genes were related to neurodegenerative diseases, such as genes related to Alzheimer’s disease: PSEN2, TREM2, and GAB2; Parkinson’s disease: ATP13A2 and DCTN1; and amyotrophic lateral sclerosis: TAF15 and FUS." (PMID 40877796, 2025). "Examples of IL-4 induced genes that are not strain specific include Chil3, whereas Trem2, which is important in Alzheimer’s disease and cancer, is an IL-4 induced gene specific for BL/6 macrophages." (PMID 39863579, 2025). "Hence, microglial TREM2 and ITAM signaling seem to play a crucial role in clearing amyloid-beta plaques in animal models of Alzheimer’s disease." (PMID 38529039, 2024). "We additionally reviewed other risk genes associated with Alzheimer’s disease (ABCA7, SORL1 and TREM2), and no relevant variants were identified." (PMID 38287166, 2024). "Recent research has elucidated that TREM2 facilitates the microglial response to amyloid-beta through independent and spleen tyrosine kinase (SYK)-dependent mechanisms, as evidenced in the 5xFAD model of Alzheimer’s disease." (PMID 39596378, 2024). "None of the TREM2 p.R47H carriers had a diagnosis of mild cognitive impairment or Alzheimer’s disease." (PMID 37990275, 2023). "In this work, protein-protein interaction analysis was conducted based upon the genes from a clinical database to identify the top protein targets with most data-indicated involvement in Alzheimer’s disease, which include ABCA1, CYP46A1, BACE1, TREM2, GSK3B, and SREBP2." (PMID 37444065, 2023). "Some observations suggest that the imbalance between TREM2 and TLR4 (toll-like receptor 4) signaling in favor of TLR4 may contribute to the development of Alzheimer’s disease." (PMID 37108808, 2023). "In addition to these two genes, the proteins SREBP2, TREM2, LRP1, and the CYP46A1 gene are all additional candidates as targets to combat Alzheimer’s disease due to their involvement in the metabolic pathway of cholesterol in the brain." (PMID 37444065, 2023).
Alzheimer disease (continued). "Whereas TREM2 deletion has been studied extensively in experimental beta-amyloid and Tau-based models of Alzheimer’s disease, its engagement, and subsequent agonism have not been tested in the context of Tau pathology." (PMID 37296669, 2023). "White matter changes and myelin alterations have been detected in Alzheimer’s disease and its mouse models, which may contribute to disease pathology, including TREM2-dependent DAM signaling; however, TREM2-independent glial responses have also been described." (PMID 36280798, 2022). "Triggering receptor expressed on myeloid cells 2 (TREM2) signaling is considered to regulate anti-inflammatory responses in macrophages, dendritic cell maturation, osteoclast development, induction of obesity, and Alzheimer’s disease pathogenesis." (PMID 33980160, 2021). "For example, several genes causing ALS and/or frontotemporal dementia (C9orf72, VCP, SQSTM1, OPTN, UBQLN2, GRN, CHMP2B) affect the autophagic machinery; and some Alzheimer’s Disease genes (APOE, TREM2, CD33, ABCA7) are preferentially or exclusively expressed in microglia." (PMID 33892821, 2021). "It is well known that mutation of TREM2 leads to NHD and Alzheimer's disease, yet its association with gliomas has not been clarified." (PMID 26506595, 2016). "However, the relationship between TREM2 and Alzheimer's disease is complicated, and there is still no consensus on the role of TREM2 in Alzheimer's disease." (PMID 38649789, 2024). "However, TREM2 p.R47H carriers had worse cognitive performance when measured by the ADAS-Cog 13 and DMS, despite none of these participants meeting the criteria for mild cognitive impairment or Alzheimer’s disease." (PMID 37990275, 2023). "The primary aim of this study was to investigate if TREM2 p.R47H risk variant carriers have reduced in vivo microglial activation, measured using TSPO signal, compared to non-carriers also at increased risk of Alzheimer’s disease." (PMID 37990275, 2023). "Triggering receptor expressed on myeloid cells 2 (TREM2), a member of the immunoglobulin superfamily, binds lipids, transmits intracellular signals via the adaptor DNAX-activating protein of 12 kDa (DAP12) and plays a critical role in the pathogenesis of Alzheimer’s disease (AD)." (PMID 37563723, 2023). "In addition, a panel of Alzheimer’s-disease relevant genes, which are consistently up-regulated in the transgenic CRND8 mouse brain over time, also reveals variable (Abi3 versus Plcg2)—and sometimes unexpected (Trem2)—responses to Aβ peptides in microglia." (PMID 34127518, 2021). "Neurofilament light (NFL), soluble TREM2 (sTREM2) and neurogranin are promising new biomarkers for Alzheimer’s disease (AD), but it is not clear whether they are specific for parenchymal amyloid." (PMID 32176643, 2020). "Interestingly, the levels of soluble TREM2 (the secreted ectodomain of TREM2, sTREM2) were higher in cerebrospinal fluid (CSF) from Alzheimer's disease (AD) patients than subjects without cognitive decline." (PMID 33768114, 2020). "Background: rs9357347 located at the triggering receptor expressed on myeloid cells (TREM) gene cluster could increase TREM2 and TREM-like transcript 1 (TREML1) brain gene expression, which is considered to play a protective role against Alzheimer’s disease (AD)." (PMID 31379492, 2019). "In addition to TREM2, it is probable that our immune module contains other determinants of neuropathology relevant to neurodegeneration more broadly: consistent with this the immune module is enriched with GWA genes for both ALS and Alzheimer’s disease." (PMID 28302159, 2017). "Moreover, finding new molecules that can act via TREML-1 could modulate the activity of TREM-2, and vice-versa On the other hand, also targeting TREML-2 could open to new strategies for the treatment of Alzheimer’s disease, highly enhancing the rate of success." (PMID 40948752, 2025).
Alzheimer disease (continued). "However, even if curcumin does not represent a new ligand for neither TREM2 or Siglec-3, these findings suggest the huge potential that could derive by controlling both TREM2 or Siglec-3 pathways involved in developing Alzheimer’s disease." (PMID 40948752, 2025). "Thus, the putative protective effects of TREM2 and sTREM2 are complimentary rather than antagonistic, and potentially both may be protective against Alzheimer's disease." (PMID 35153729, 2021). "In diseases like Alzheimer's disease, the lack of DAP12 and dysfunction of TREM2 lead to a reduced ability of microglial cells to clear β-amyloid plaques, accelerating neurodegeneration and worsening the disease's pathological progression." (PMID 40153574, 2025).
amyloid (134 papers, 2014 to 2026). "Although numerous studies have reported that TREM2 expression is upregulated in amyloid plaque-associated microglia in vivo, our research is the first to show that PU.1 knockdown abrogates this phenomenon in vitro." (PMID 40376093, 2025). "Studies in amyloid mouse models have demonstrated that the loss of functional TREM2 impairs microglial clustering around amyloid plaques, reducing microglial phagocytic capacity and leading to inefficient amyloid clearance." (PMID 40247363, 2025). "Inhibition or loss-of-function mutations of TREM2, such as the R47H variant, impair microglial phagocytosis of amyloid plaques and increase amyloid seeding in mouse models of AD." (PMID 41301546, 2025). "The only significant gene in both NMES and control comparisons is Trem2, the deficiency of which was shown to diminish microglia barrier and amyloid plaque growth in AD mouse models." (PMID 40869172, 2025). "Emerging evidence suggests that the timing of microglial activity is crucial for amyloid pathology: TREM2 deficiency was found to ameliorate amyloid pathology early but exacerbate it late in the APPPS1-21 AD model mice." (PMID 39695808, 2024). "For example, in the AD rodent model of APPPS1 mice, the lack of neuroinflammation-related gene TREM2 expression (i.e., TREM2 deficiency) lowered amyloid pathologies at the earlier stage of disease development but worsened it at the later stage." (PMID 39075118, 2024). "In the PS19 model, deletion of TREM2 resulted in significantly less brain atrophy and ameliorated the microgliosis phenotype; by contrast, in the 5xFAD model, TREM2 deficiency exacerbated amyloidosis and neuronal loss." (PMID 38600001, 2024). "Higher levels of soluble TREM2 are associated with slower amyloid accumulation in amyloid-positive individuals and slower tau deposition and cognitive decline in amyloid and tau-positive individuals." (PMID 36981033, 2023). "To investigate the effects of H157Y mutation on AD-related amyloid pathogenesis, we crossed Trem2 H157Y knock-in mice with 5xFAD amyloid model mice." (PMID 36721205, 2023). "Taken together, our findings suggest beneficial effects of the Trem2 H157Y mutation in synaptic function and in mitigating amyloid pathology." (PMID 36721205, 2023). "Adeno-associated virus-mediated soluble TREM2 (sTREM2) expression reduces amyloid plaque load and rescues spatial memory and LTP deficits in 5XFAD mice." (PMID 34074018, 2021). "What is the causal link between FAAH deletion and TREM2 overexpression in the presence of amyloid pathology?" (PMID 34587978, 2021). "Similar plaque morphology with less fibrillar Aβ, as observed in APP-KI mice, has also been reported in AD mice deficient for TREM2 or APOE that also have less microglial cells recruited to amyloid plaques and display prominent neuritic dystrophies." (PMID 32510331, 2020). "Determining the outcome of TREM2 gene loss, haplodeficiency or variants on microglia-mediated synaptic loss in mouse models of amyloid and Tau pathology is an important topic of investigation." (PMID 33408613, 2020). "TREM2 knockout in the APPPS1 mice was associated with increased Aβ seeding induced amyloid plaque burden at 6 months of age." (PMID 32790063, 2020). "A recent study reported that TREM2 deficiency has a disease-progression-dependent effect on amyloid pathology by ameliorating amyloid pathology early but exacerbating it late in AD in APPPS1-21 mice." (PMID 32257540, 2020). "To determine the role of Trem2 in the progression of amyloid disease pathology, we crossed PS2APP mice with Trem2-deficient mice and examined plaque-related phenotypes in single-sex groups at various stages of pathology." (PMID 31980586, 2020). "Overall, these data suggest that a decrease in TREM2 protein levels is associated with early-stage vascular amyloid pathology and early synaptic impairment in this CAA model." (PMID 32711525, 2020).